ACE (angiotensin I converting enzyme)
Diseases named in the same sentence as ACE in open-access papers (continued):
Sharing a sentence is not in itself a finding about the gene and the disease.
Hypertension (continued). "The most important finding of the present study is that we have manufactured miso with potent ACE inhibitory activity and that this miso may work as an ACE inhibitor to attenuate hypertension." (PMID 30631160, 2019). "Moreover, in animal models, DNA hypomethylation in the promoter regions of Agtr1b, Agtr1a and ACE was also found to be correlated with hypertension; those studies strongly support the consequence of epigenetic modification of the hypertension programming." (PMID 30691489, 2019). "ACE inhibition is an important method often used to treat high blood pressure." (PMID 31086041, 2019). "In the remaining models, the ACE I/D polymorphism gene did not have significant association with essential hypertension." (PMID 30763326, 2019). "The Angiotensin Converting Enzyme (ACE) Insertion/Deletion and rs-4343 gene polymorphisms could be associated with pathogenesis of essential hypertension and cardiovascular disorders and Coronary Artery Disease (CAD)." (PMID 30800252, 2019). "Exceptions are the prescription of certain classes of antihypertensive drugs if they have additional benefits for co-existing conditions, e.g. ACE inhibitors to treat hypertension and prevent progression of kidney disease or beta blockers to treat hypertension and heart failure." (PMID 29999442, 2018). "The method developed in this study may potentially be applied to prepare efficient ACE-inhibitory peptides, which may play a key role in hypertension management." (PMID 30081563, 2018). "Sampatrilat (UK 81252, (S,S,S)‐N‐{1‐[2‐carboxy‐3‐(N‐mesyllysylamino)propyl]‐1‐cyclopentylcarbonyl}tyrosine) is a vasopeptidase or dual inhibitor of ACE and neutral endopeptidase with potential application in the treatment of hypertension and congestive heart failure." (PMID 29476645, 2018). "CPG 2008 recommended ACE inhibitors as drug of choice in hypertension with renal disease." (PMID 29721335, 2018). "In addition, pancreatic lipase and ACE are also therapeutic targets in the treatment of obesity and hypertension, respectively." (PMID 30274353, 2018). "One of the most widely used drug types for treatment of hypertension is ACE inhibitors." (PMID 29266709, 2018). "Recently, investigators have described that Pleurotus ostreatus, P. cystidiosus, P. cornucopiae, Auricularia auricula-judae, Ganoderma leucocontextum, Grifola frondosa, Agaricus bisporus and Leucopaxillus tricolor are all ACE inhibitors that decrease hypertension." (PMID 30400600, 2018). "In the renovascular system, it has been reported that renal vasodilator response to l-arginine was abolished in untreated essential hypertension, while the same responses were restored when the hypertension was treated with angiotensin converting enzyme (ACE) inhibitors." (PMID 30177600, 2018). "ACE inhibitors have been reported to diminish mortality in patients with hypertension." (PMID 30400600, 2018). "Angiotensin‐converting enzyme (ACE) affects the development of hypertension." (PMID 29266709, 2018). "Inhibition of ACE by ACE inhibitors is a strategy used to control hypertension." (PMID 29545737, 2018). "Since postnatal HF diet resulted in higher systemic ANG peptides and AGT in adipose tissue, ACE inhibitors and ANG II receptor blockers may be more suitable treatments for HF diet associated hypertension." (PMID 29540174, 2018). "Therefore, ACE inhibitors are primary drugs to treat hypertension, a common cardiovascular disease, which is one of the major risk factors of several other cardiovascular diseases, such as stroke, coronary heart disease, and myocardial infarction." (PMID 29854760, 2018). "Here we demonstrate that in the Gata1low murine model of spontaneous myelofibrosis a 2‐month administration of captopril, an ACE inhibitor commonly used for the treatment of systemic hypertension, decreased bone marrow megakaryocytic hyperplasia and marrow fibrosis." (PMID 29971909, 2018).
Hypertension (continued). "miR-483-3p expression downregulated angiotensinogen and angiotensin-converting enzyme (ACE) and could be a novel therapeutic agent for hypertension management." (PMID 29914215, 2018). "This signifies that treatment with ACE inhibitor might only be indicated for the part of angina patients with hypertension." (PMID 29883497, 2018). "This correlates with the increased pancreatic β-cell and serum insulin level as ACE inhibitors have been shown to be not just therapeutic against hypertension but also reduces the risk of type 2 diabetes and its complications." (PMID 29449808, 2018). "Therefore, a key to the treatment and prevention of hypertension is the effective inhibition of ACE activity." (PMID 30373231, 2018). "Therefore, the inhibition of ACE has been considered the first-line target in the prevention and the treatment of hypertension." (PMID 29973522, 2018). "Interestingly, miRNAs regulating the gene of ACE were differentially expressed in both hypertension and exercise, like the exercise-induced increase of miR-27a (targeting ACE) and miR-155 (targeting AT1R) and the decrease of miR-143 (targeting ACE2)." (PMID 30445764, 2018). "Hypertension and proteinuria were treated with an ACE inhibitor and candesartan." (PMID 29946535, 2018). "The angiotensin-converting enzyme (ACE) is an important target and has broad effects in different systems, and ACE inhibitors were originally developed for the treatment of congestive heart failure, diabetic kidney disease, and hypertension management." (PMID 30477129, 2018). "Moreover, miR-27a has been shown to be associated with the renin-angiotensin system (RAS) and contribute to modulate the cardiovascular homeostasis and against aortic injury in hypertension by targeting ACE gene." (PMID 29304813, 2018). "In the univariate linear regression analysis of twist, the presence of hypertension, diabetes, the use of ACE inhibitor or angiotensin receptor blocker (ARB), and change in weight before and after dialysis were compared against the difference in apical, basal and net twist before and after dialysis." (PMID 29750229, 2018). "Therefore, ACE inhibition has been proven to be an effective therapeutic target for prevention and treatment of hypertension." (PMID 30453595, 2018). "The ACE inhibitor was used for arterial hypertension on a daily basis for the past 5 years." (PMID 30075570, 2018). "ACE is a zinc-containing metalloproteinase that catalyses the conversion of angiotensin I to angiotensin II, the latter is a potent vasoconstrictor involved in the pathogenesis of hypertension." (PMID 30060542, 2018). "In recent decades, the most successful strategy to treat hypertension is the inhibition of ACE." (PMID 29854760, 2018). "Therefore, the inhibition of ACE has been extensively used as a therapeutic strategy for the prevention and treatment of hypertension and has been found to improve endothelium-dependent vasorelaxation." (PMID 29849899, 2018). "Furthermore, APOE, NOS3, ACE, AGT, and CYP variants influence the therapeutic response to hypotensive drugs in AD patients with hypertension." (PMID 29301387, 2018). "Clinical characteristics including age, smoking history, alcohol drinking, hypertension, hyperlipemia, diabetes mellitus, family history, and body mass index (BMI, kg/m2) and the administration of β-blockers and ACE inhibitors were all collected from the patients." (PMID 30407292, 2018). "Therefore, Coriandrum sativum was explored for the identification and characterization of more bioactive compounds with known ACE inhibition mechanism of action against hypertension." (PMID 30581531, 2018). "Therefore, it is quite essential to study the inhibition of ACE in order to prevent and manage hypertension." (PMID 30081563, 2018). "ACE inhibition is an important therapeutic approach in the treatment of high blood pressure." (PMID 29494506, 2018).
Hypertension (continued). "More than a dozen ACE inhibitors have been used extensively in the treatment of essential hypertension and heart failure in humans; these include alacepril, benazepril, captopril, cilazapril, enalapril, fosinopril, lisinopril, moexipril, perindopril, quinapril, ramipril, tandolapril, and zofenopril." (PMID 30248998, 2018). "Therefore, inhibition of ACE activity is considered to be a useful therapeutic approach for the treatment of hypertension." (PMID 30248998, 2018). "Therefore, ACE and renin inhibitor makes a positive contribution to hypertension treatment and specific inhibitors are currently used in pharmaceuticals." (PMID 28282929, 2017). "Thus, inhibitors of ACE are widely used in the therapy for hypertension—for instance, captopril, enalapril and lisinopril." (PMID 28098801, 2017). "ACE is a member of the M2 family metallopeptidase and have an important role in hypertension." (PMID 28333109, 2017). "Current findings have indicated that ACE inhibitors may increase NO bioavailability and reduce oxidative and nitrosative stress parameters during hypertension." (PMID 29234376, 2017). "Further assessment should be done for early signs of nephropathy such as microalbuminuria and hypertension, with management (with ACE inhibitors or LDL-lowering “statin” drugs) being informed by the forthcoming results of the Adolescent Type 1 Diabetes Cardio-Renal Intervention Trial (ADDIT)." (PMID 28948172, 2017). "We found that the D allele of the ID polymorphism in the ACE gene was significantly associated with hypertension and with obesity-related traits in boys, but not in girls." (PMID 28903744, 2017). "If these were combinations with an ACE inhibitor or with an angiotensin receptor blocker, as recommended in current international hypertension guidelines, the incidence rates of calcium channel blocker-related adverse events would be typically reduced compared with monotherapy." (PMID 29290834, 2017). "Serum FT4 levels (β = 0.27 ± 0.12, P = 0.03) and age (β = 0.11 ± 0.03, P < 0.01) were positively associated with PASP adjusted for age, gender, BMI, smoking, LVEF, hypertension, and use of calcium channel blockers, ACE inhibitors, angiotensin II receptor antagonists, and nitrates." (PMID 28717364, 2017). "Finally, for anti-hypertension activity, SE-EA also demonstrated the strongest inhibitory activity on ACE (IC50 = 626.6 ± 15.0 μg/mL)." (PMID 29065451, 2017). "The variants of angiotensin converting enzyme (ACE) and matrix metalloproteinases (MMPs) genes might be involved in the pathogenesis of end stage renal disease (ESRD) and hypertension." (PMID 28447048, 2017). "After adjustment of age, gender, BMI, smoking, LVEF, hypertension, and use of calcium channel blockers, ACE inhibitors, angiotensin II receptor antagonists, and nitrates, FT4 levels were independently associated with the risk of PH (OR = 1.12, 95% CI 1.01–1.25, P = 0.03)." (PMID 28717364, 2017). "Therefore, development of food protein hydrolysates with an ACE-inhibitory effect is considered to be a safe alternative to the use of the synthetic ACE inhibitors in the management of hypertension." (PMID 28362352, 2017). "Age, weight, hypertension and ACE Inhibitors did not affect genetic associations with warfarin dose requirements." (PMID 28638342, 2017). "However, it was found that any single currently used ACE inhibitor cannot completely prevent and cure hypertension." (PMID 29099799, 2017). "The results suggest that EA at bilateral PC6 could arrest the hypertension development and ameliorate the cardiac hypertrophy and malfunction in SHRs, which might be mediated by the regulation of ACE, AT1R, and AT2R." (PMID 28293268, 2017). "Counting exposures (rather than patients), 50% were in male patients, 16% were in African-American patients, 9% were in smokers, 32% had diabetes, 78% had hypertension, 24% had coronary artery disease, 7% congestive heart failure, and 17% were on an ACE inhibitor." (PMID 28603715, 2017).
Hypertension (continued). "For example, a patient with type 2 diabetes, hypertension and osteoarthritis may be prescribed one or more oral hypoglycaemic agents, an angiotensin converting enzyme (ACE) inhibitor, other anti-hypertensive agents, a statin, aspirin, and an analgesic." (PMID 28587644, 2017). "Therefore, in the development of drugs to control high blood pressure, ACE inhibitors and angiotensin receptor blockers are now used clinically for the treatment of various cardiovascular diseases." (PMID 28761878, 2017). "This research suggests that peppers of the Capsicum genus may be useful as dietary cofactors in hypertension management, and especially in ACE-dependent hypertension." (PMID 27158555, 2016). "Moreover, numerous potent domain-selective ACE inhibitors are available clinically, and generally effective in the treatment of hypertension, post-myocardial infarction and diabetic nephropathy." (PMID 27758878, 2016). "In this context, ACE I/D polymorphism association studies in Egyptians are very limited, with few reports linking it to hypertension and diabetes, but none of them addressed its correlation with obesity." (PMID 27777603, 2016). "Hydrolyzed proteins of animal origin may show ACE‐inhibitory activity, which is central to the treatment of hypertension." (PMID 27004118, 2016). "Thus, the inhibition of ACE is considered as an effective strategy in designing pharmaceutical drugs for the treatment of hypertension." (PMID 27271639, 2016). "Hypertension was not independently associated, but antihypertensive treatment with β blockers, calcium channel blockers and ACE-inhibitors was associated with a higher AF risk." (PMID 27021333, 2016). "Catalysis of angiotensin I to angiotensin II causes increase in blood pressure, and therefore inhibition of ACE may help in the management of hypertension." (PMID 26927038, 2016). "It is well-accepted that either ACE inhibitors or AT1 blockers are the gold standard drugs in order to manage hypertension, due their survival benefits provided on patients with heart failure, high cardiac risk profile and also proteiunuric chronic kidney disease." (PMID 27992423, 2016). "However, the patients with established hypertension were seen to be more likely to need a change in treatment if they were being treated with an ACE-inhibitor (OR, 0.61; 95 % CI, 0.41–0.92)." (PMID 26956148, 2016). "Thus, given the biological effects of these variants, it would be expected that the combination of risk genotypes, in this case DD of ACE, CC of rs699 and CC of AGTR-1, confer greater likelihood of developing MetS, DM2, hypertension and cardiovascular disease." (PMID 26910623, 2016). "Several clinical studies have demonstrated that AT-II receptor antagonists such as candesartan, eprosartan, losartan, irbesartan, tasosartan, telmisartan, and valsartan are as effective as ACE inhibitors for the treatment of hypertension; furthermore, they induce fewer adverse effects." (PMID 26867195, 2016). "In addition, the administration of the Mas receptor antagonist, A-779 in experimental models of hypertension, attenuated the effects of ACE inhibitors and Ang II receptor blockers." (PMID 27635280, 2016). "This suggests that the endothelium dysfunction might be a secondary event of NF-κB → ACE → Ang II → Reactive oxygen species → NF-κB positive feedback signal pathway during the development of hypertension in prenatal inflammation-induced offspring." (PMID 26877256, 2016). "Specifically in the lung, inhibition of bradykinin metabolic breakdown by ACE inhibitors or exogenous administration of B2 receptor agonists exerted protective effects, reducing pulmonary arterial pressure in experimental hypertension and neutrophil recruitment by lipopolysaccharide." (PMID 26909880, 2016).
Hypertension (continued). "Several soil‐derived Actinobacteria produce secondary metabolites that are proven specific and potent inhibitors of the human angiotensin‐I‐converting enzyme (ACE), a key target for the modulation of hypertension through its role in the renin–angiotensin–aldosterone system." (PMID 27754586, 2016). "The plasma levels of ACE activity tended to be positively related to BP changes, which is consistence with the earlier work that have shown that ACE levels could be used as a hypertension marker in SHRs." (PMID 26857237, 2016). "Moreover, inhibitors for ACE are widely used to treat cardiovascular diseases like hypertension and heart failure." (PMID 27678063, 2016). "The ACE inhibitor enalapril and angiotensin II receptor blocker losartan were also shown to exert antifibrotic effects in hypertension and may have similar cardioprotective effects in diabetes by similar mechanisms." (PMID 27642609, 2016). "In these patients, who are the majority, suppression of the activity of the renin–angiotensin system by angiotensin-converting enzyme (ACE), or angiotensin II receptor antagonism, is effective in both controlling the BP and reducing the complications of hypertension." (PMID 27774451, 2016). "A few drugs for the treatment of hyperglycemia, hypertension, and dyslipidemia (metformin, thiazolidinediones, ACE inhibitors, ARBs, statins, and ezetimibe) might have protective activity on liver disease, while others are expected to worsen the disease." (PMID 27123461, 2016). "Pomegranate juice may be able to prevent the development of high blood pressure due to angiotensin II in diabetes via inhibition of angiotensin converting enzyme (ACE)." (PMID 27158555, 2016). "ACE inhibitors such as captopril are used by a large number of people to control hypertension." (PMID 26918946, 2016). "Therefore, inhibition of ACE has become a promising way for regulation and treatment of high blood pressure." (PMID 27834876, 2016). "Guidelines from JNC-7 recommend diuretics for most patients as initial therapy for hypertension, however use of ARBs, calcium channel blockers, beta blockers, and ACE inhibitors may also be appropriate based on compelling clinical indications." (PMID 25738503, 2015). "Thus, ACE inhibitors or ARBs are recommended as the first step in the treatment of type 2 diabetic patients with hypertension." (PMID 25938807, 2015). "The majority of patients (33/35, 94%) in the EVR group were treated with an ACE-inhibitor or angiotensin-receptor-antagonist from month 1 post-transplant on because of arterial hypertension, while in the control group only 49/70 patients (70%) were treated with any antihypertensive medication." (PMID 26407177, 2015). "However, in type 2 diabetic patients with hypertension that is inadequately controlled using ACE inhibitors or ARBs, the additional use of antihypertensive medications is controversial." (PMID 25938807, 2015). "In comparison to the multicenter cohort study TRIBE-AKI, our single-center cohort included more male patients with higher prevalence of hypertension, congestive heart failure, presurgical cardiac catherization, ACE inhibitor or ARB medication, and worse preoperative kidney function." (PMID 26669323, 2015). "If hypertension persists after use of a beta-blocker plus an ACE inhibitor or ARB, a long-acting dihydropyridine CCB may be added to the therapeutic regimen." (PMID 26718096, 2015). "The D allele particularly in homozygous (DD) state is associated with high level of circulating ACE resulting in an increased activity of angiotensin II which may predispose the individual to a variety of disorders including T2DM and hypertension." (PMID 26491214, 2015). "It was therefore important to assess the association of ACE I/D polymorphism with hypertension in diabetic and nondiabetic groups separately." (PMID 26491214, 2015).